CCL5 (C-C motif chemokine ligand 5)
Diseases named in the same sentence as CCL5 in open-access papers (continued):
Sharing a sentence is not in itself a finding about the gene and the disease.
influenza (continued). "We found that empagliflozin treatment decreased the expression of IL-6, CCL2, and CCL5 in BMDMs and IL-6 and CCL2 in RAW264.7 macrophages during influenza infection." (PMID 38112660, 2023). "The study also revealed strengthened interactions of the Ccl5-Ccr5, Ccl4-Ccr5, and Ccl3-Ccr5 ligand/receptor pairs between CD8+ Trm and other memory subsets after influenza infection." (PMID 37415817, 2023). "During influenza, cytokines and chemokines such as type I and III interferons (IFNs), IL-6, CXCL8, CCL2, CCL3, CCL4, and CCL5 are produced at the site of infection (Wareing and others 2004)." (PMID 35674675, 2022). "Akin with that, mice lacking the CCL5 scavenger Atypical Chemokine Receptor 2 (ACKR2) present increased CCL5 levels, CCR5+CD4+ lymphocyte recruitment to the airways and augmented levels of IgA in the BALF during influenza." (PMID 35126379, 2021). "Interestingly, a recent study provided strong evidence for the protective role of CCR5 antagonism during Chronic Obstructive Pulmonary Disease (COPD) exacerbations caused by influenza in which CCL3 levels but no CCL5, correlated with an exacerbated inflammatory process." (PMID 35126379, 2021). "Other chemokines elevated in influenza-infected Tpl2-/- mice, including CXCL10, CCL5, CCL3 and CCL4, are also overexpressed in human cases of lethal influenza infections and recognized for recruitment of inflammatory monocytes and neutrophils." (PMID 34691044, 2021). "Influenza infection induced a variety of inflammatory cytokines such as IL-1β, IL-6, TNFα, IL-8, CCL2, CCL5, and CXCL10 from epithelial and immune cells." (PMID 30337919, 2018). "Influenza infection also induces the production of such cytokines as TNFa, IL-1, IL-6, and the mononuclear cell attractant chemokines: CCL-3, CCL-4, CCL-5, CXCL9, CXCL10, and CXCL11 in human monocytes, epithelial cells, and rat alveolar or murine macrophages." (PMID 30037133, 2018). "The concentrations of the cytokines IL-1β, IL-6, TNF-α, CXCL1,CXCL2, CCL5, IFN-γ and IL-12p40 were evaluated in lung homogenates ofcontrol and Influenza infected mice." (PMID 21079759, 2010). "As one of the natural ligands of CCR5, CCL5/CCR5 can mediate the recruitment and activation of neutrophils and monocytes during influenza, and CXCL1 can chemotactic T cells, monocytes, neutrophils and other immune cells when combined with its specific CXCR2 receptor." (PMID 37957672, 2023). "Whilst influenza infection increased the production of pro-inflammatory cytokines and chemokines, as with RSV infection, treatment with vitamin D either before or after influenza infection decreased gene expression of TNF-α, IFN-β, ISG15, CXCL8, IL-6 and RANTES (CCL5)." (PMID 26035247, 2015). "In previous studies mice lacking SPP1 and CCL5 were found to clear influenza infection with no adverse effects, while mice lacking CCR2 survived infection by a mouse-adapted influenza A virus that killed wild-type mice." (PMID 22189154, 2011). "In response to influenza viral entry, epithelial and immune cells induce pro-inflammatory cytokines and chemokines such as interleukin-1β, interleukin-6, tumor necrosis factor α (TNFα), CCL2, CCL3, and CCL5, which recruit macrophages and neutrophils to the site of infection to control the virus." (PMID 39846844, 2025). "Although the chemokine receptor CCR5 does not actively participate in the infection process of influenza, after its activation by the chemokines CCL3/MIP-1α, CCL4/MIP-1β, and CCL5/RANTES, it becomes a key player in the inflammatory milieu that contributes to infection restraint." (PMID 35126379, 2021).
HIV-1 infection (50 papers, 2007 to 2025). The type species of lentivirus and the etiologic agent of acquired immunodeficiency syndrome (AIDS). "Their analysis indicated significant associations of the -403G/A and -28C/G polymorphisms in the RANTES/CCL5 gene with protection against HIV-1 infection." (PMID 37766364, 2023). "Prior meta-analyses have explored the associations between the same SNPs in the RANTES/CCL5 gene and susceptibility to HIV-1 infection contexts." (PMID 37766364, 2023). "With respect to the association between RANTES/CCL5 SNPs and HIV-1 infection, the most frequently examined genetic variants for susceptibility to HIV-1 were rs2107538 and rs2280788." (PMID 37766364, 2023). "The present review included three SNPs (rs2107538, rs2280788, and rs2280789) to evaluate their relationship with the RANTES/CCL5 gene and HIV-1 infection." (PMID 37766364, 2023). "CCL4, together with CCL5 (RANTES) and CCL3, is produced by CD8+ T cells and is a suppressive factor for HIV-1 infection; recombinant CCL4, CCL5 and CCL3 block HIV-1 infection of susceptible cells in vitro." (PMID 35967369, 2022). "Given their competitive binding to the CCR5 receptor, the chemokines MIP-1α, MIP-1β and CCL5 (RANTES) were shown to inhibit HIV-1 infection in cells." (PMID 32098198, 2020). "It was also shown that CCL5/glycosaminoglycan complexes are able to bind to deglycated PBMC and thereby block HIV-1 infection more effectively than CCL5 alone." (PMID 19068144, 2008). "Study by Wen and colleagues also showed that expression of CCL3, CCL4 and CCL5 decreased in U937 promonocytes in response to HIV-1 infection." (PMID 17684570, 2007). "Indeed, previous data suggested a relation between the RANTES/CCL5 polymorphisms and the likelihood of HIV-1 infection and progression." (PMID 37766364, 2023). "Beyond HIV-1 infection, these CCL5 derivatives may now be tested against several inflammation-related pathologies where the CCL5:CCR5 axis plays a relevant role." (PMID 29382912, 2018). "CCL5/CCR5 interaction has been reported in a number of Th1-associated diseases, such as rheumatoid arthritis, multiple sclerosis, human immunodeficiency virus 1 (HIV-1) infection, Crohn’s disease, and oral lichen planus." (PMID 27776524, 2016). "For example, a higher expression of genes encoding the chemokine CCL5, heme oxygenase-1 (HMOX-1), thioredoxin reductase, peroxiredoxins, glyceraldehyde-3-phosphate dehydrogenase (GAPDH), etc. are host defense mechanisms well known to negatively regulate HIV-1 infection and replication (77, –, 81)." (PMID 25406321, 2015). "HIV-1 infection of human macrophages leads to the release of β-chemokines including CCL2, CCL3, CCL4, and CCL5." (PMID 38005838, 2023). "Although several studies have investigated the influence of HIV-1 infection and disease progression on circulating levels of CCL3, CCL4 and CCL5, results have been contradictory." (PMID 34987508, 2021). "Upon HIV-1 infection of MDMs, we also observed a higher level of ISG induction in MDMs from older donors, including IRF5, as well as several known IRF5-responsive genes, such as CXCL16, CCL5, and CD80." (PMID 40493408, 2025). "These upregulated genes were primarily ISGs, including IRF5 and IRF7, as well as several known IRF5 target genes, including CCL5, CXCL16, and IL23A, suggesting that MDMs from older individuals display an enhanced IRF5-dependent innate immune response to HIV-1 infection." (PMID 40493408, 2025). "In addition to CCL2, other CC chemokines, namely CCL3, CCL4 and CCL5, are constitutively released by MDM and their production can be further increased following HIV-1 infection of these cells." (PMID 25608886, 2015). "CCL5 appears to be an immune correlate of protection because infants born to HIV-infected mothers who remain uninfected show higher levels of RANTES (regulated on activation, normal T cell expressed and secreted) than do infants with perinatal HIV-1 infection." (PMID 24367701, 2013).
HIV-1 infection (continued). "The first encounter between the fields of HIV and chemokines occurred unexpectedly at the end of 1995 with the discovery that three chemokines of the CC family, RANTES (CC-chemokine ligand 5 or CCL5), MIP-1α (CCL3) and MIP-1β (CCL4), act as potent and specific natural inhibitors of HIV-1 infection." (PMID 21284904, 2011). "CCL3, CCL4, CCL5 and CXCL12 are important natural inhibitors of HIV-1 infection, and it possible that the activation of chemokine receptors may stimulate chemokine expression." (PMID 21264298, 2011). "The CC-chemokines CCL3, CCL4 and CCL5 have been found to block the entry of CCR5-tropic HIV into host cells and to suppress the viral replication in vitro, but the in vivo role of endogenous CC-chemokines in HIV-1 infection is still incompletely understood." (PMID 17684570, 2007).
rheumatoid arthritis (48 papers, 2008 to 2025). A chronic, systemic autoimmune disorder characterized by inflammation in the synovial membranes and articular surfaces. "Increase CCL5 levels has been reported in rheumatoid arthritis (RA), and positive patient responses to methotrexate therapy have been associated with CCL5 reductions." (PMID 26985768, 2016). "T cell CXCR3 and its ligands CXCL9 and CXCL10 as well as CCR5 and its ligands CCL3 and CCL5 are expressed at higher levels in disorders where Th1 immune responses predominate such as multiple sclerosis and rheumatoid arthritis." (PMID 36670847, 2023). "In a study of patients with rheumatoid arthritis and periodontitis, CCL5 levels in GCF also correlated with cigarette smoking." (PMID 38139161, 2023). "In particular CD103+ CD69+ CD8 T resident memory (Trm) cells were found in elevated numbers in previously inflamed joints in rheumatoid arthritis (RA), and shown to initiate flares by recruiting circulating lymphocytes by CCL5 secretion." (PMID 35720379, 2022). "It is also consistent with one study that showed that LTαβ, which only binds LTβR, induced mRNA or protein expression of ICAM-1, and several chemokines including CCL5, in rheumatoid arthritis-derived fibroblast-like synoviocytes." (PMID 29616048, 2018). "Rheumatoid arthritis synovial fibroblasts were treated with RANTES/CCL5 for 5, 15, and 30 min and the expression of p-c-Jun and p-ATF-2 was determined in the nuclear extracts." (PMID 29093715, 2017). "Moreover, we again confirmed the downregulation of the expression levels of rheumatoid arthritis-associated genes, including IL-6, CCL20, and CCL5 using the RT-PCR analysis." (PMID 37777063, 2024). "In rheumatoid arthritis and OA, upregulation of CCL5 levels in serum or synovial fluid has been reported, which may participate in the migration of monocytes, T cells, natural killer cells and eosinophils." (PMID 36769097, 2023). "According to previous studies, CCL5 is directly associated with disturbed bone metabolism in nonpainful rheumatoid arthritis." (PMID 35659283, 2022). "The CCL-5 augmented on KC patients may suggest local inflammation once this chemokine is related to many other inflammatory situations like angiogenesis, cancer, upper airway, and rheumatoid arthritis." (PMID 37460969, 2023). "Moreover, CCL5 is thought to be important for leukocyte extravasation, thus facilitating the migration of these cells into the CNS and has also been described to be responsible for recruiting monocytes and memory T cells in rheumatoid arthritis (RA)." (PMID 36717913, 2023). "Regulated on activation, normal T expressed, and secreted (RANTES)/CC ligand 5 (CCL5) participates in rheumatoid arthritis (RA) pathogenesis by facilitating leukocyte infiltration, however, its other pathological functions are not fully defined in RA." (PMID 29093715, 2017). "Recently, increased miR-155 is shown to be associated with increased production of the chemokines CCL3, CCL4, CCL5 and CCL8, and regulate chemokine receptor expression in rheumatoid arthritis patients." (PMID 29162878, 2017). "CCL5 has been shown to facilitate (CCR5-mediated) interactions in multiple inflammatory disorders, and both chemokines are suggested as targets for treating CRS, graft-versus-host disease, and rheumatoid arthritis among others." (PMID 40894883, 2025). "While CCL5 induces matrix metalloproteinase (MMP) production in rheumatoid arthritis, its role in OA is not yet well defined." (PMID 39684859, 2024). "Moreover, high levels of inflammatory/arthrogenic factors, including cytokines (TNF-α, IL-6, IL-7, IL-15, and BAFF) and chemokines (CCL-2, CCL-5, and CXCL-10) have been reported in the serum and/or synovia of rheumatoid arthritis patients." (PMID 38720890, 2024). "Additionally, the KEGG pathway analysis showed 14 pathways (p < 0.05) related to potential targets, and CCL5, MMP3 and MMP1 were enriched in the rheumatoid arthritis pathway." (PMID 36615560, 2023).
rheumatoid arthritis (continued). "One study showed that patients with periodontitis and rheumatoid arthritis had higher levels of CCL5 in the GCF than patients with periodontitis but no rheumatoid arthritis, but the differences were not statistically significant (p = 0.087)." (PMID 38139161, 2023). "We previously observed that mature osteoclasts highly expressed C-C chemokine receptor type 5 (CCR5) and that CCR5 and C-C motif chemokine ligand 5 (CCL5), a major ligand for CCR5, were involved in bone-destructive diseases, such as osteoporosis and rheumatoid arthritis." (PMID 36769097, 2023). "In addition, a positive correlation between CCL5 levels in GCF and age has been observed in studies of patients with rheumatoid arthritis and periodontitis." (PMID 38139161, 2023). "However, a study of rheumatoid arthritis patients with periodontitis showed that CCL5 levels in GCF were not correlated with the patients’ BMI." (PMID 38139161, 2023). "Rheumatoid arthritis may not affect CCL5 production in the gingiva of patients with periodontitis." (PMID 38139161, 2023).
gastric cancer (46 papers, 2011 to 2025). A primary or metastatic malignant neoplasm involving the stomach. "The study indicated that KLF5 promoted the invasive and metastatic abilities of tumor cells by activating the CCL5/CCR5 axis in gastric cancer-associated fibroblasts." (PMID 35589690, 2022). "The conclusion is that the CCL5/CCR5 axis seems associated with gastric cancer progression due to increased growth and metastasis formation." (PMID 24523569, 2014). "Liou and colleagues indicated that women who inherit A allele of CCL5 rs2107538 may be at reduced risk of gastric cancer." (PMID 36983384, 2023). "CCL5 was overexpressed in cancerous tissues and serum of gastric cancer patients, and its level was closely related to the differentiation, growth, pathological stage, invasion, and metastasis of gastric cancer." (PMID 39003350, 2024). "CCL5 expression was also positively correlated with TAM surface marker CD68, showing the involvement of TAMs in the development and metastasis of gastric cancer through secreting CCL5." (PMID 39003350, 2024). "17β-estradiol has also been reported to inhibit the migration of gastric cancer cells by inhibiting CCL-5 and the IL-6-induced phosphorylation of Src, Cas, and paxillin in human gastric cancer cells." (PMID 37175948, 2023). "Several studies have revealed that the up-regulation of CCL4 and CCL5 in gastric carcinoma, tongue squamous cell carcinoma (TSCC), and colon cancer resulted in the initiation of invasion steps." (PMID 38067251, 2023). "Compared to healthy volunteers, the serum level of CCL5 of gastric cancer patients was also increased, and increased exogenous CCL5 level enhanced the migration ability of AGS cells across the transwell membrane." (PMID 34367971, 2021). "CCL5, CCL22, CCL21, CCL2, and CCL15 were correlated with effector memory CD4 T cell in T1/T2 stage gastric cancer, and the number of cells was associated with the expression of IL3, IL17F, IL18, IL22, and IL31." (PMID 33426088, 2020). "Some of these chemokines and receptors, such as CXCL13, CCL4, CCL5, CCR2, CXCR3, and CXCR4, have been experimentally confirmed to be associated with the pathogenesis or prognosis of gastric cancer or other malignancies." (PMID 32685487, 2020). "Gastric cancer cells exposed to CCL5 were shown to induce apoptosis of CD8+ T cells and infiltration of T-regulatory cells as an immune escape mechanism." (PMID 31505877, 2019). "We show that the infection of KDM4B-knockdown cells led to the reduced production of IL-8 as well as CXCL1 and CCL5, which are chemokines involved in gastric cancer progression." (PMID 30683841, 2019). "Supernatants from high-metastatic gastric cancer cell lines increase CCL5 expression in PBMC, as compared to PBMC stimulated by supernatants of low-metastatic cells." (PMID 24523569, 2014). "Following infection with Helicobacter pylori in a gastric cancer model system CCL5 is elevated and its levels are reduced by treatment with anti-inflammatory drugs." (PMID 24523569, 2014). "Increased CCL5 levels are expressed by human gastric cancer cell lines characterized by a high metastatic potential suggesting a tumor-promoting role of CCL5 in gastric cancer." (PMID 24523569, 2014). "Several authors have then analyzed CCL5 expression in gastric cancer and found a possible correlation with the formation of metastasis." (PMID 24523569, 2014). "Gastric cancer cells exploit CCL5, not only for their own growth, but also to assist in evasion of the host immune system." (PMID 24523569, 2014). "With regard to immune escape mechanisms, cancer cells exposed to CCL5 have also been shown to induce apoptosis of CD8+ T cells in gastric cancer." (PMID 22205974, 2011). "Moreover, we found that CCL5 mRNA expression was upregulated in these chemoresistant gastric cancer cells." (PMID 39827154, 2025). "Therefore, suppressive immune microenvironment and ST3G5 and CCL5 expression in gastric cancer and other tumors should be examined in future studies." (PMID 37716915, 2024).